CCDC74B (coiled-coil domain containing 74B)
Synonyms: DKFZp434E2321
Tractability: No criterion of Open Targets' tractability assessment is met for any kind of drug.
Gene: Protein-coding gene on chromosome 2 (130,139,287 to 130,145,134, reverse strand). Ensembl gene ENSG00000152076.
Subcellular location (Human Protein Atlas): Basal body; Centrosome; Cytosol; Nucleoplasm
Genetic constraint (gnomAD): Loss-of-function variants: 34 observed, 35.53 expected, observed/expected ratio (o/e) 0.96, 90% interval 0.73 to 1.27. The upper end of that interval is the gene's LOEUF score, 1.27, which puts it in group 5 of 6, group 1 being the genes least tolerant of losing a copy. Missense variants: 352 observed, 367.98 expected, observed/expected ratio (o/e) 0.96, 90% interval 0.88 to 1.04. Synonymous variants: 130 observed, 151.63 expected, observed/expected ratio (o/e) 0.86, 90% interval 0.74 to 0.99.
Homologues: Orthologues: chimpanzee CCDC74B (98% identical), mouse Ccdc74a (68% identical), rat Ccdc74a (68% identical). Paralogues in human: CCDC74A (97% identical).
Diseases named in the same sentence as CCDC74B in open-access papers:
CCDC74B is named in the same sentence as 2 diseases in open-access papers, as found by Europe PMC text mining. Sharing a sentence is not in itself a finding about the gene and the disease.
CCDC74B shares sentences with these, for which no sentence is quoted: asthma (1 paper); lung disease (1).